TEX101 (testis expressed 101)
Description:
Plays a role in fertilization by controlling binding of sperm to zona pellucida and migration of spermatozoa into the oviduct (By similarity). May play a role in signal transduction and promote protein tyrosine phosphorylation (By similarity).
Synonyms: SGRG; MGC4766; CT131; SPATA44; TES101RP; GTPR867; NYD-SP8; PRO1884
Tractability: Antibody: its Gene Ontology location is reachable by antibodies, with high confidence; UniProt places it where antibodies can reach, with medium confidence; UniProt predicts a signal peptide or a membrane-spanning region.
Gene: Protein-coding gene on chromosome 19 (43,401,496 to 43,418,597, forward strand). Ensembl gene ENSG00000131126.
Subcellular location: Cell membrane; Membrane raft; Cytoplasmic vesicle, secretory vesicle, acrosome; Secreted; Cytoplasmic vesicle
Pathways (Reactome):
Metabolism of proteins: Post-translational modification: synthesis of GPI-anchored proteins
Gene Ontology:
Biological process: binding of sperm to zona pellucida; fertilization; flagellated sperm motility; regulation of flagellated sperm motility
Cellular component: acrosomal vesicle; cytoplasmic vesicle; extracellular region; membrane raft; plasma membrane; plasma membrane raft; acrosomal membrane
Genetic constraint (gnomAD): Loss-of-function variants: 10 observed, 19.38 expected, observed/expected ratio (o/e) 0.52, 90% interval 0.32 to 0.88. The upper end of that interval is the gene's LOEUF score, 0.88, which puts it in group 3 of 6, group 1 being the genes least tolerant of losing a copy. Missense variants: 259 observed, 315.34 expected, observed/expected ratio (o/e) 0.82, 90% interval 0.74 to 0.91. Synonymous variants: 94 observed, 121.12 expected, observed/expected ratio (o/e) 0.78, 90% interval 0.66 to 0.92.
Homologues: Orthologues: chimpanzee TEX101 (98% identical), macaque TEX101 (87% identical), dog TEX101 (59% identical), guinea pig TEX101 (57% identical), rabbit TEX101 (54% identical), mouse Tex101 (54% identical), pig TEX101 (53% identical), rat Tex101 (49% identical). Paralogues in human: CD177 (29% identical), LYPD4 (24% identical).
Diseases named in the same sentence as TEX101 in open-access papers:
TEX101 is named in the same sentence as 27 diseases in open-access papers, as found by Europe PMC text mining. Sharing a sentence is not in itself a finding about the gene and the disease. The quoted sentences say what the papers report.
Azoospermia (9 papers, 2017 to 2024). Absence of any measurable level of sperm,whereby spermatozoa cannot be observed even after centrifugation of the semen pellet. "The expression level of TEX101 protein is significantly decreased in the seminal plasma of azoospermia patients, compared with normal males, and the concentration of TEX101 in seminal plasma is related to the number of testicular germ cells." (PMID 36624393, 2023). "Men after vasectomy, patients with Sertoli cell-only syndrome and men with obstructive azoospermia had only undetectable levels of the TEX101 protein, while in seminal plasma of fertile men, the protein was well detectable." (PMID 37568830, 2023). "In this study, we focused on a germ-cell-specific protein TEX101 that we previously identified and validated as a seminal plasma biomarker for the differential diagnosis of azoospermia and male infertility (53, –55)." (PMID 30429210, 2019). "Our previous work on TEX101 as a biomarker of azoospermia motivated us to generate monoclonal antibodies and develop a first-of-a-kind TEX101 ELISA." (PMID 28330469, 2017). "We previously verified human TEX101 as a biomarker for the differential diagnosis of azoospermia, and developed a first-of-its-kind TEX101 ELISA." (PMID 28330469, 2017). "In 2013, TEX101 was first suggested as a biomarker for the differential diagnosis of azoospermia." (PMID 33882832, 2021). "TEX101 levels were broadly distributed in the azoospermia group with the unknown form (median 0.6 ng/mL), NOA with the unknown histological subtype (0.6 ng/mL), and in NOA-HS (70.4 ng/mL) and NOA-MA (1.9 ng/mL)." (PMID 28330469, 2017). "TEX101 median values were estimated in healthy, fertile pre-vasectomy men (5436 ng/mL, N = 64) and in patients with unexplained infertility (4967 ng/mL, N = 277), oligospermia (450 ng/mL, N = 270), and azoospermia (0.5 ng/mL, N = 137)." (PMID 28330469, 2017). "As a result, the combination of TEX101 and ECM1 showed an almost exclusive discrimination between the azoospermia conditions." (PMID 37568830, 2023). "All azoospermia cases diagnosed as NOA by ECM1 ≥ 2.3 μg/mL and TEX101 ≥ 0.9 ng/mL will thus be correct (32 patients), while 19% of patients diagnosed as OA based on ECM1 < 2.3 μg/mL and TEX101 < 0.9 ng/mL (eight patients in the current set) will be actually NOA (false negatives)." (PMID 28330469, 2017). "Very low levels were observed in the samples with no spermatozoa.TEX101’s predicted phenotypes include both azoospermia (HP:0000027) and abnormal spermatogenesis (HP:0008669) obtained from the Human Phenotype Ontology database, with z-scores of 6.5 and 5.9 respectively." (PMID 35774118, 2022). "TEX101 was not a useful marker of unexplained infertility (AUC = 0.56, 95% CI 0.48–0.63, P > 0.05), but performed well in oligospermia (AUC = 0.88, 95% CI 0.84–0.92, P < 0.001) and azoospermia (AUC = 0.99, 95% CI 0.98–1.00, P < 0.001)." (PMID 28330469, 2017). "The combination of a concentration of TEX101 > 0.9 ng/mL and epididymis-specific protein ECM1 > 2.3 μg/mL provided 81% sensitivity at 100% specificity for differentiating between non-obstructive and obstructive azoospermia, thus eliminating the majority of diagnostic testicular biopsies." (PMID 28330469, 2017). "The same group developed a multiplex selected reaction monitoring (SRM) assay to detect the level of testis-expressed protein 101 (TEX101) and epididymis-expressed extracellular matrix protein 1 (ECM1) to distinguish men with obstructive azoospermia from those with non-obstructive azoospermia." (PMID 29704899, 2018).
infertile (6 papers, 2016 to 2025). "In a preclinical evaluation using the ELISA method on seminal plasma samples from 805 individuals, TEX101 levels were found to be significantly lower in males with infertility compared to the fertile controls." (PMID 40458181, 2025). "Highest TEX101 values were observed in fertile men and in men from couples with unexplained infertility, and far lower levels in patients with reduced sperm concentration." (PMID 35774118, 2022). "Results confirmed the presence of TEX101 in SMVs and vesicle-free fractions of the four-sample infertility pool, as well as of the pre-vasectomy pool." (PMID 28330469, 2017). "While reviewing the results, however, we noticed that 17 samples from the unexplained infertility and oligospermia groups with a substantial sperm count (≥7 million/mL) exhibited undetectable levels of TEX101 in SP." (PMID 28330469, 2017). "The GndCl-based protocol was compromised only in some infertility samples with low TEX101 levels (<300 ng/mL)." (PMID 28330469, 2017). "Although both Tex101−/− and Ly6k−/− mice can produce morphologically intact spermatozoa, both knockout mice show an infertile phenotype due to a disorder of spermatozoa to migrate into the oviduct." (PMID 27005865, 2016). "A lack of TEX101 was also indicative of an infertile phenotype, due to the loss of the ability for the sperm to migrate into the oviduct." (PMID 35774118, 2022). "Our initial hypothesis for mutant TEX101 protein in the infertile men was rejected by detection of TEX101 in both SP and corresponding spermatozoa by mass spectrometry." (PMID 28330469, 2017). "In addition, we noticed that a small fraction of patients (N = 17) with unexplained infertility (sperm count >15 million/mL) and oligospermia (sperm count >7 million/mL) had undetectable levels of TEX101 (<0.5 ng/mL) in SP." (PMID 28330469, 2017). "However, when TEX101 levels are very low (<300 ng/mL in the infertility pool), the impact of SMVs becomes significant." (PMID 28330469, 2017). "In infertile men, incubation of the original pool and the vesicle-free fraction with DOC at 63 °C identified a significantly higher level of TEX101 than pretreatment with GndCl at RT." (PMID 28330469, 2017). "In the last decade, only four reproductive tract-specific genes with infertile mouse models have been identified that fit the criteria of being expressed as early as the spermatogonia stage: ASZ1, MOV10L1, SCML2, and TEX101." (PMID 32161754, 2020).
male infertility (6 papers, 2015 to 2025). The inability of the male to effect fertilization of an ovum after a specified period of unprotected intercourse. "TEX101 protein is a validated biomarker of male infertility and a potential germ cell-surface chaperone." (PMID 30429210, 2019). "The presence of TEX101 in seminal plasma may be of relevance in the investigation of male infertility, being a potential biomarker." (PMID 35774118, 2022). "TEX101 is a germ-cell-specific protein and a validated biomarker of male infertility." (PMID 30429210, 2019). "It has been reported that deficiency of the genes with similar expression profile, such as Zmym3, Ku70, Fam46d, Pdha2, Tex101 and Spata19, etc. always resulted in spermatogenic problems leading to male infertility, thus validating the essential roles of these genes." (PMID 29563520, 2018). "We hypothesized that TEX101 levels in SP would vary in patients with different categories of male infertility." (PMID 28330469, 2017). "Several promising biomarkers for male infertility and prostate cancer include ECM1, TEX101, LDHC, TKTL and ACPP proteins, and prostate specific antigen (PSA), TMPRSS2-ETS." (PMID 26097523, 2015).
breast cancer (4 papers, 2012 to 2025). A primary or metastatic malignant neoplasm involving the breast. "In this study we tried to show the expression of three cancer testis genes, TSGA10, TEX101 and ODF3 in breast cancer patients as well as breast cancer cell lines." (PMID 23396665, 2012). "ELISA test was performed for detection of antibody against TSGA10, TEX101 and ODF3 in serum of breast cancer patients and normal healthy controls." (PMID 23396665, 2012). "In conclusion, the expression of three CT antigens, TSGA10, TEX101 and ODF3 were checked in breast cancer patients." (PMID 23396665, 2012). "In this study we determined the expression of cancer testis genes Tsga10, TEX101 and ODF3 in patients with breast cancer." (PMID 23396665, 2012). "RT-PCR of patients’ tumor samples and breast cancer cell lines were carried out using specific primers for TSGA10, PIWIL2, TEX101 and ODF3 genes." (PMID 23396665, 2012). "This study hypothesized that epigenetic processes, including DNA methylation, influence the expression of identified CG or testis-specific genes, such as SYCP1, ADAD1, SYCE1, PRSS54, DMRTC2, and TEX101, in breast cancer (BC), normal breast (NB), and chronic myelogenous leukemia (CML) cell lines." (PMID 41411337, 2025). "Previous research has also shown that TEX101 expression was absent in all breast cancer specimens and cell lines tested, whereas TEX101 overexpression was observed in head and neck carcinoma and chronic myeloid leukemia." (PMID 39208330, 2024). "In addition, the active expression of some testis-specific genes, including testis specific-10 (TSGA-10), testis expressed-101 (TEX101), and the outer dense fiber of sperm tails-3 (ODF-3), has already been approved in breast cancer as the cancer–testis (CT) gene." (PMID 41009526, 2025). "None of breast cancer samples and cell lines showed expression of TEX101 and ODF3." (PMID 23396665, 2012). "ELISA test for TEX101 and ODF3 was negative in all breast cancer and normal control serums (Figurs 3,4,5)." (PMID 23396665, 2012).
Sertoli Cell-Only Syndrome (4 papers, 2017 to 2025). A type of male infertility in which no germ cells are visible in any of the biopsied SEMINIFEROUS TUBULES (type I) or in which germ cells are present in a minority of tubules (type II). "TP53I11 and EDDM3B were also associated with Sertoli cell-only syndrome and TEX101, EDDM3B, and PLCZ1 with varicocele." (PMID 40497989, 2025). "The levels of TEX101 above 120 ng/mL of seminal plasma were confirmed as a manifestation of normal spermatogenesis; values from 5 to 120 ng/mL are associated with hypospermatogenesis and values below 5 ng/mL indicate Sertoli cell-only syndrome." (PMID 37568830, 2023). "Fertile post-vasectomy men (N = 57) and patients with Sertoli cell-only syndrome (N = 13) and obstructive azoospermia (N = 36) had undetectable levels of TEX101 (≤0.5 ng/mL)." (PMID 28330469, 2017). "Furthermore, TEX101, at a threshold >5 ng/mL, could differentiate NOA underlined by Sertoli-cell only syndrome from NOA due to other testis histology (e.g., hypospermatogenesis, with a 67% specificity and a 100% sensitivity, or maturation arrest, with a 54% sensitivity and a 100% specificity)." (PMID 33022946, 2020).
chronic myelogenous leukemia (3 papers, 2022 to 2025). "TEX101 overexpression in individuals with chronic myeloid leukemia may be attributable to the hypomethylation of this gene." (PMID 39208330, 2024). "A study among patients with chronic myeloid leukaemia showed expression of TEX101 in blood samples of 30% of patients compared to no expression in controls." (PMID 35774118, 2022).
seminoma (3 papers, 2014 to 2022). A radiosensitive malignant germ cell tumor found in the testis (especially undescended), and extragonadal sites (anterior mediastinum and pineal gland). "The loss of TEX101 expression in seminoma also suggested its potential role in the progression of testicular cancer." (PMID 25418358, 2014). "In this study, the expression features of TEX101 in normal human organs and seminoma were systematically analyzed." (PMID 25418358, 2014). "Investigating of the different histology patterns showed that despite the increased positive log2fc in non-seminomas, there are still RNA signals, such as mRNA TEX101, that are independent of the histology." (PMID 33251139, 2020). "Furthermore, we examined seminoma tissues by immunohistochemistry and found that none of the 36 samples expressed TEX101." (PMID 25418358, 2014). "The lack of TEX101 in seminoma indicated its potential role in tumor progression." (PMID 25418358, 2014). "Investigating TEX101 expression in seminoma TGCT tissues demonstrated a similar finding, revealing no expression of TEX101, in contrast to normal testis." (PMID 35774118, 2022).
basal cell carcinoma (2 papers, 2012 to 2022). A carcinoma involving the basal cells. "This study also noted that TEX101 expression was significantly higher in high-risk basal cell carcinomas than in the low-risk tumours." (PMID 35774118, 2022). "Previously, our studies showed expression of TEX101, SPATA19 and LEMD1 in basal cell carcinoma and prostate cancer." (PMID 23396665, 2012). "Expression of TEX101 has been demonstrated in 38% of basal cell carcinoma tissue samples compared to the absence of expression in normal skin tissue samples." (PMID 35774118, 2022).
bladder carcinoma (1 paper, 2021). "However, overexpression of urothelial carcinoma-associated 1α (UCA1α), which promotes bladder carcinoma progress, decreased the level of TEX101 in bladder carcinoma." (PMID 34966825, 2021). "It indicates that TEX101 and TEX10 play different roles in bladder carcinoma." (PMID 34966825, 2021).
Fibroadenoma (1 paper, 2012). A benign tumor of the breast characterized by the presence of stromal and epithelial elements. "ANCT and fibroadenoma tissues also were negative for TEX101 and ODF3 expression." (PMID 23396665, 2012).
head and neck squamous cell carcinoma (1 paper, 2022). A squamous cell carcinoma that arises from any of the following anatomic sites: lip and oral cavity, nasal cavity, paranasal sinuses, pharynx, larynx, and salivary glands. "In patients with head and neck squamous cell carcinoma (HNSCC), 81% of patients showed TEX101 expression in cancer cells with an absence of TEX101 in the healthy tissue of controls." (PMID 35774118, 2022).
leukemia (1 paper, 2025). A malignant (clonal) hematologic disorder, involving hematopoietic stem cells and characterized by the presence of primitive or atypical myeloid or lymphoid cells in the bone marrow and the blood. "We comprehensively analyzed differential methylation, survival analysis (Kaplan-Meier), correlation (Spearman’s), and pathway enrichment analysis (GO/KEGG) of CG genes (SYCP1, ADAD1, SYCE1, PRSS54, DMRTC2, and TEX101) in BC and leukemia." (PMID 41411337, 2025). "DMRTC2 showed elevated methylation in leukemia (~0.80 vs. ~ 0.60), whereas TEX101 was higher in healthy blood (~0.85 vs. ~ 0.60)." (PMID 41411337, 2025). "For leukemia patients, SYCE1 again displays relatively prolonged survival, while PRSS54 and TEX101 are linked to a more rapid decline." (PMID 41411337, 2025). "The minimal enrichment of TEX101 in BC but high impact in leukemia underscores its context-dependent roles." (PMID 41411337, 2025). "The inverse methylation-expression correlation of SYCE1 in leukemia (ρ = −0.45) suggests epigenetic silencing, whereas TEX101’s positive correlation in BC implies alternative activation mechanisms." (PMID 41411337, 2025). "In leukemia versus healthy donors, GO enrichment revealed that TEX101, ADAD1, PRSS54, and SYCE1 were the most enriched genes, whereas SYCP1 and DMRTC2 exhibited minimal enrichment." (PMID 41411337, 2025). "In leukemia, SYCE1 and TEX101 dominated pathway analysis, potentially regulating hematopoietic differentiation." (PMID 41411337, 2025). "The contrasting 5-aza-CdR responses in breast versus leukemia models (SYCP1: 8–10-fold induction vs 0.01-fold suppression; TEX101: 2-fold vs 0.2-fold) underscore how cellular context dictates epigenetic vulnerability." (PMID 41411337, 2025).
lung carcinoma (1 paper, 2022). "Cancer Cell Line Encyclopaedia (CCLE) also showed TEX101 gene CNVs profiles and expression profiles in many cancer cell lines, including multiple lung cancer cell lines (LXF-289, NCI-H2087, NCI-H889), where TEX101 exhibits both high and low expression associations." (PMID 35774118, 2022).
melanoma (1 paper, 2022). A malignant, usually aggressive tumor composed of atypical, neoplastic melanocytes. "In a human melanoma cell line HMCB, TEX101 shows one of the lowest expressed genes, with a standardised value of -3.0." (PMID 35774118, 2022).
oligospermia (1 paper, 2017). Decreased number of spermatozoa in the semen. "We initially measured TEX101 in 821 SP samples obtained from healthy fertile men pre- and post-vasectomy, as well from patients with unexplained infertility, oligospermia, and OA and NOA." (PMID 28330469, 2017).
small cell lung carcinoma (1 paper, 2022). Small cell lung cancer (SCLC) is a highly aggressive malignant neoplasm, accounting for 10-15% of lung cancer cases, characterized byrapid growth, and early metastasis. "For example, in the small cell lung cancer cell line CORL95, TEX101 was one of the most highly expressed genes, with a standardised expression value of 3.4." (PMID 35774118, 2022).